PRMT6 (protein arginine methyltransferase 6)
Diseases named in the same sentence as PRMT6 in open-access papers (continued):
Sharing a sentence is not in itself a finding about the gene and the disease.
cancer (continued). "Since PRMT6 was identified more than 20 years ago, many studies have been performed to identify the characteristics and molecular functions of PRMT6 in cancer." (PMID 35311114, 2022). "As a result, many PRMT6 inhibitors are being utilized to explore their efficacy as potential drugs for various cancers." (PMID 35311114, 2022). "Meanwhile, PRMT6 negatively regulates DNA methylation, and the upregulation of PRMT6 contributes to global DNA hypomethylation in cancer." (PMID 35311114, 2022). "This necessitates studies that investigate the efficacy of PRMT6 specific inhibitors for cancer therapy." (PMID 34575100, 2021). "The high levels of PRMT6 in cancer cells lead to the global DNA hypomethylation and contribute to the carcinogenesis, possibly through the passive DNA demethylation." (PMID 34575100, 2021). "We expect that these insights will foster the rational development and usage of specific PRMT6 inhibitors for cancer therapy." (PMID 34001852, 2021). "This will enable the rational development and usage of specific PRMT6 inhibitors for cancer therapy." (PMID 34001852, 2021). "Additional studies are required to resolve this conundrum as to why enhanced levels of PRMT6 have opposing effects in different cancers." (PMID 34575100, 2021). "All these findings establish that PRMT6 is an important potential therapeutic target for various cancers." (PMID 34575100, 2021). "Consistent with our findings, a recent study reported that PRMT6 methylate PTEN at Arg159 to repress AKT signaling, and Arg159 mutation within PTEN contributes to cancer development." (PMID 33260152, 2020). "We compared the expression level of PRMT6 in 24 matched samples from cancer tissues and adjacent normal tissues from the same patients by western blotting." (PMID 29507670, 2018). "Among the clinicopathological parameters, the ratio of poorly differentiated cancer cells was approximately two-fold higher in patients with PRMT6-positive disease than in those with PRMT6-negative disease (p = 0.002)." (PMID 29507670, 2018). "DNA-damaging chemotherapy in combination with a PRMT6 inhibitor is expected to improve the clinical outcome of anti-cancer treatment." (PMID 26436589, 2015). "We conclude that PRMT6 promotes cell growth and prevents senescence, thus, making it potential target for cancer therapy." (PMID 22987071, 2012). "Since p21 has been discussed as a promising target for cancer therapeutics, modulation of PRMT6 activity should be considered as a target of pharmaceutical drug design." (PMID 22916108, 2012). "To clarify detailed functions of PRMT6 in cancer, we performed IP-MS analysis and identified MCM7 as a binding partner (data not shown)." (PMID 21619671, 2011). "Moreover, specific asymmetric dimethylarginine antibody (R729me2a) was employed to measure STAT3’s R729me2a levels in cancer cells expressing Vector, PRMT6 WT, or PRMT6 KLA mutant." (PMID 37813837, 2023). "Likewise, Kaplan–Meier Plotter database analysis reinforced these observations, illustrating an inverse correlation between PRMT6 expression levels and overall survival time across multiple cancer types." (PMID 37813837, 2023). "Moreover, Transwell assays were employed to gauge the migration and invasion potential of cancer cells stably expressing Vector + sgRNA-Control, PRMT6 + sgRNA-Control, and PRMT6 + sgRNA-STAT3." (PMID 37813837, 2023). "Thus, the PRMT6/PARP1/CRL4B complex maintains carcinoma progression by reducing the amplitude of circadian rhythms and circadian oscillations." (PMID 36941223, 2023). "Therefore, PRMT6 promotes cell growth and prevents senescence, thus becoming an anti-tumor therapeutic target for various types of cancer." (PMID 35311114, 2022). "Therefore, PRMT6 can be regarded as a new research target for tumor therapy, and the study of PRMT6 inhibitors has also become a hot spot to explore potential cancer treatment approaches." (PMID 35311114, 2022). "We will also note that PRMT6 is a potential target for cancer therapy." (PMID 35311114, 2022).
cancer (continued). "Taken together, the elevated levels of PRMT6 are linked to carcinogenesis of many different types of cancers mediated through methylation of histone or non-histone substrates and/or protein interactions." (PMID 34575100, 2021). "Indeed, PRMT6 expression inversely correlates with global DNA methylation in many human cancer cells, and PRMT6 depletion or inhibition restores DNA methylation." (PMID 34006904, 2021). "In the following sections, we will discuss the role of PRMT6 in different cancer types." (PMID 34575100, 2021). "It should be pointed out that the binding of pUL69 to PRMT6 could be another mechanism elucidating its role in cancer development." (PMID 33937031, 2021). "PRMT6 methylates PTEN at Arg135, which is frequently mutated in cancer." (PMID 34575100, 2021). "In the following sections, we discuss the biochemical features, structural aspects, epigenetic functions of PRMT6, functional outcomes of PRMT6-mediated methylation of non- histone substrates and viral proteins and the role of PRMT6 in various types of cancers." (PMID 34575100, 2021). "We detected nuclear expression of PRMT6 in 23.7% of carcinoma samples by immunohistochemistry." (PMID 29507670, 2018). "Given that nuclear localization is required for cell-cycle arrest of cancer cells by p21, PRMT6-mediated R156 methylation may impair growth suppressive functions of p21 due to the promotion of its cytoplasmic subcellular localization in cancer cells." (PMID 26436589, 2015). "In addition, we show evidence that translocation of p21 regulated by PRMT6-mediated arginine methylation affect chemosensitivity of cancer cells." (PMID 26436589, 2015). "Our results indicate that PRMT6 appears to be one of the key proteins to dysregulate p21 functions in human cancer, and targeting this pathway may be an appropriate strategy for development of anticancer drugs." (PMID 26436589, 2015). "Given that the induction of p21-mediated growth suppressive functions is considered as a critical mechanism for several anticancer agents such as HDAC inhibitors and that PRMT6 is significantly overexpressed in various types of cancer, PRMT6 is likely to be a promising anti-cancer drug target." (PMID 26436589, 2015). "Overexpression of PRMT1 and PRMT6 has been previously reported in various cancer types." (PMID 22987071, 2012). "Despite its overexpression in a variety of cancer tissues, a causal link demonstrating that the upregulated enzymatic activity of PRMT6 is essential for malignant transformation has not been established." (PMID 22987071, 2012). "Further functional analyses may make clear the cooperation of PRMT6 in the MCM complex in human cancer." (PMID 21619671, 2011). "PRMT6 contributes to the initiation and progression of cancer by regulating gene expression, enhancing cell proliferation and migration, modulating signalling pathways, regulating cancer cell metabolism, and promoting the self‐renewal and differentiation of tumour stem cells." (PMID 39964832, 2025). "Therefore, inhibition of PRMT6-mediated p62 ADMA could be a new option to sensitize ferroptosis for cancer treatment." (PMID 38994016, 2024). "Therefore, targeting PRMT6-mediated p62 ADMA could be a new option to sensitize ferroptosis for cancer treatment." (PMID 38994016, 2024). "In addition, PRMT6 also plays different roles in various cancers via influencing cell growth, migration, invasion, apoptosis, and drug resistant, which make PRMT6 an anti-tumor therapeutic target for a variety of cancers." (PMID 35311114, 2022).
cancer (continued). "Furthermore, PRMT6 inhibitors are anticipated to become new tumor therapeutic targets because of their synergistic effects on tumor cells and components of the tumor microenvironment, which may make them particularly successful in cancer therapy." (PMID 41154773, 2025). "On the other hand, five pleiotropic loci were detected in the all-cancer meta-analysis (e.g., IGF2BP2 on 3q27, PRMT6 on 1p13, and TRIM4 on 7q22)." (PMID 37340002, 2023). "Ten mammalian PRMTs have been identified to date, of which PRMT1, CARM1, PRMT5, PRMT6, and PRMT9 are found to be highly expressed in several cancers and correlate with poor overall survival." (PMID 37760550, 2023). "It has been found that PRMT6 is frequently down-regulated in HCC, and its expression is negatively correlated with aggressive cancer characteristics in HCC patients." (PMID 35311114, 2022). "PRMT6 catalyzes CRAF methylation to decrease its RAS binding and alter its downstream MEK/ERK signaling to inhibit the cancer stemness activities of hepatocellular carcinoma." (PMID 33260152, 2020). "Notably, PRMT6 has been found overexpressed in many types of human cancers; therefore, the facilitation of NF-κB nuclear shuttling could be an important mechanism contributing to NF-κB-dependent gene activation in cancer." (PMID 24939901, 2014). "Together, our data support developing inhibitors that are selective for PRMT1 and PRMT3, but not for PRMT4 and PRMT6, to eliminate cancer persistence." (PMID 39699269, 2025). "Thus, as measured by MTT assays and flow cytometry, both PRMT6 and RBM39 maintained cancer cell growth and CSC-like properties under Indisulam treatment, unlike E155/164A or R92K." (PMID 40465651, 2025). "Such as, PRMT6 asymmetrically di-methylates STAT3 at arginine-729 (R729) and this modification is essential for membrane localization of STAT3, interaction with JAK2, phosphorylation of STAT3 Y705, and PRMT6-driven cancer cell metastasis." (PMID 40164592, 2025). "Subsequently, co-immunoprecipitation assays were undertaken to ascertain whether PRMT6 could physically bind to STAT3, and the results disclosed a substantive interaction between PRMT6 and STAT3 in MCF-7 and MDA-MB-468 cancer cells." (PMID 37813837, 2023). "Our subsequent xenograft study underscored that PRMT6 overexpression led to a significant increase in lung metastasis nodes and weight while shortening the overall survival time of mice harboring STAT3 WT cancer cells." (PMID 37813837, 2023). "Notably, consistent findings were replicated in cancer cells treated with Vector + DMSO, PRMT6 + DMSO, and PRMT6 + stattic." (PMID 37813837, 2023). "In cancer tissues of GSE25097, the expressions of PRMT2, PRMT3, PRMT4, PRMT5, and PRMT7 were upregulated in cancer tissues, whereas the expressions of PRMT6 and PRMT9 were downregulated." (PMID 37627211, 2023). "Collectively, our findings illuminate the potential benefits of targeting PRMT6 as a therapeutic strategy to counteract both the STAT3 signaling pathway and the H3R2-mediated epigenetic mechanisms, offering new avenues for enhancing cancer treatment outcomes." (PMID 37813837, 2023). "Transwell assays further bolstered our observations, showing that PRMT6 enhancement distinctly amplified the migration and invasion capabilities of cancer cells with STAT3 WT, yet failed to manifest this effect in cells with STAT3 R729K mutant." (PMID 37813837, 2023). "To delve deeper into the intricate interplay between PRMT6 and STAT3 R729 methylation in the context of tumor metastasis, we engineered MDA-MB-468 cancer cells to stably express various combinations: STAT3 WT+ vector, STAT3 WT + PRMT6, STAT3 R729K+ vector, and STAT3 R729K + PRMT6." (PMID 37813837, 2023). "Interestingly, cells from cancer patients showed higher PRMT1 and PRMT6 expression than cells from healthy tissue, which seemed to be beneficial for tumor growth." (PMID 36172281, 2022).
cancer (continued). "Although the detailed mechanism of PRMT6 activity on proliferation in cancer is not yet identified, the recruitment of PRMT6 by transcription factors to target genes involved in cell-cycle regulation is part of this process." (PMID 34001852, 2021). "Not surprisingly, downregulation of PRMT6 across these cancer types leads to a reduction in cell proliferation and invasiveness through different mechanisms." (PMID 34575100, 2021). "PRMT6 depletion induces cell cycle arrest and senescence in several types of cancer cell lines; however, PRMT6-mediated apoptosis in cancer cells has not been previously reported." (PMID 29507670, 2018). "Other results have established that PRMT6 is more highly expressed in cancer cells than in non-neoplastic cells." (PMID 26690413, 2015). "Similar to our results from tumours and normal tissue, we found PRMT6 to be overexpressed at the RNA and protein levels in cancer lines as opposed to MCF10A normal breast epithelial cells." (PMID 22987071, 2012). "Recently, CARM1/PRMT4 and PRMT6 were found to be overexpressed in a variety of human cancers compared to non-neoplastic tissues." (PMID 22916108, 2012). "In summary, PRMT6 belongs to the type I PRMT family and functions by methylating histone or non-histone proteins to control gene expression, stimulate or inhibit signal transduction, promote tumor stem cell self-renewal and differentiation, and promote cancer cell proliferation and migration." (PMID 41154773, 2025). "Our findings highlighted that PRMT6 overexpression significantly elevated the expression of Vimentin, twist, and N-cadherin, while concurrently downregulating E-cadherin expression in cancer cells expressing STAT3 WT, but not in those expressing STAT3 R729K mutant." (PMID 37813837, 2023). "However, the biological significance of PRMT6 in cancer is not yet clear." (PMID 38637831, 2024). "Therefore, PRMT6 can promote or inhibit cancer development, and its effect is not single and fixed." (PMID 35311114, 2022).
tumor (39 papers, 2011 to 2026). "Several studies have found that overexpression of PRMT1, PRMT3, and PRMT6 is associated with increased progression and invasiveness of many tumor types." (PMID 38663941, 2024). "Overexpression of PRMT6 caused significant augmentation of subcutaneous tumor growth, whereas PRMT6 knockdown caused the opposite result, relative to the control." (PMID 36941223, 2023). "Therefore, PRMT6 promotes lung tumor progression by modulating the alternate activation of tumor-associated macrophages (TAMs)." (PMID 35311114, 2022). "Inhibiting PRMT6 with MS023 or mutating the RBM39 methylation site enhances Indisulam sensitivity in NSCLC and significantly improves its anti-tumor efficacy." (PMID 40465651, 2025). "Promotion of immune evasion characteristics in tumor cells: PRMT6 can facilitate the epithelial-to-mesenchymal transition (EMT), invasion, and metastasis through various mechanisms." (PMID 41154773, 2025). "This indicates that PRMT6 affects tumor cells’ adaptation and survival to microenvironmental pressures by regulating the methylation of autophagy-related proteins." (PMID 41154773, 2025). "Recent studies have revealed that PRMT6 is not only an epigenetic modification enzyme but also a key driver of tumor immune evasion, influencing the tumor immune microenvironment (TIME) through various mechanisms." (PMID 41154773, 2025). "MTT and colony formation assay showed that PRMT6 overexpression alleviated the inhibitory effects of RBM39 knockout on tumor cell proliferation." (PMID 40465651, 2025). "Our findings suggested that PRMT6-mediated methylation of RBM39 promotes tumorigenicity in tumor cells." (PMID 40465651, 2025). "To further validate the observation, we analyzed the expression of PRMT1, PRMT4, and PRMT6 in fresh frozen lung tumor tissue and found elevated expression of all three PRMTs in tumor tissue compared to adjacent uninvolved tissue." (PMID 38303720, 2024). "Compared to the control group, the PRMT6 inhibitor suppressed tumor growth in vivo, and the boundary between tumor tissue and surrounding normal brain tissue in the PRMT6 inhibitor group was relatively clear." (PMID 38637831, 2024). "Immunohistochemistry (IHC) of clinical samples revealed that YTHDF2 expression increases with tumor grade and correlates positively with PRMT6 expression." (PMID 38637831, 2024). "Compared to tumor tissues, PRMT6 expression is significantly lower in normal brain tissues recorded in the GTEXBrain database." (PMID 38637831, 2024). "In line with the in vitro results, knockdown of p62 or PRMT6 significantly inhibited in vivo tumor growth compared to control shNC cells with RSL3 administration." (PMID 38994016, 2024). "In summation, our comprehensive findings provided robust confirmation that STAT3 R729 methylation constituted an indispensable factor in PRMT6-mediated tumor metastasis." (PMID 37813837, 2023). "Cohen’s κ was performed to determine if there was an agreement between the three scoring systems regarding the classification of tumor tissues to PRMT6 high vs. PRMT6 low." (PMID 37760550, 2023). "These collective findings underscored the potential of PRMT6 as a viable therapeutic target in the context of STAT3-driven tumor metastasis." (PMID 37813837, 2023). "This modification was revealed to be pivotal for various key aspects of STAT3 signaling, including its cellular membrane localization, interaction with JAK2, Y705 phosphorylation, and ultimately, PRMT6-mediated tumor metastasis." (PMID 37813837, 2023). "PRMT6 regulation of the cell cycle of tumor cells has been reported in previous studies, and we also verified cell cycle is arrested at G0/G1 phase after PRMT6 silencing in GBM cells." (PMID 36792756, 2023). "In summation, these comprehensive results underscored that PRMT6-mediated tumor cell metastasis indeed hinges on STAT3 activation." (PMID 37813837, 2023).